TBK1 (TANK binding kinase 1)
Diseases named in the same sentence as TBK1 in open-access papers (continued):
Sharing a sentence is not in itself a finding about the gene and the disease.
tumor (continued). "Thus, phosphorylated TBK1 (pTBK1) and production of specific cytokines downstream of IRF3, such as CXCL10, can be measured as a function of STING activation, which plays important roles in tumor cells, antigen presenting cells, and potentially other cell types." (PMID 33013881, 2020). "Our findings indicated that DDX58, MAVS, C6orf150, IKBKE, TBK1, and IRF3 expression were not significantly correlated with tumor purity." (PMID 38817870, 2024). "Inhibition of TBK1, but not global IRF3 knockout, reduced tumor growth, F4/80+ macrophage infiltration, and pZyxin+ cells proportion." (PMID 39304793, 2024). "The cGAS-STING pathway can exert anti-tumor effects independent of IFNs and autophagy, which mainly depends on the recruitment ability of STING to TBK1." (PMID 37965570, 2023). "In consistent, we found that the protein expressions of STING, cGAS, p-IRF3, p-TBK1, and PD-L1 were increased in the irradiated tumor although the protein expressions of IRF3 and TBK1 were not increased." (PMID 35847556, 2022). "On one hand, it promotes tumor progression through non-immune mechanisms, while on the other hand, it leads to CD8 T cell functional depletion by up-regulating TRIM14 to continuously activate the TBK1-IFNβ pathway." (PMID 39161768, 2024). "Our results showed that TBK1 expression was higher in the bile ducts with CCA and lower in the adjacent bile ducts with tumour invasion, and no TBK1 expression was detected in adjacent nontumor tissues (including the left hepatic duct, interlobular bile duct, and capillary bile duct)." (PMID 36928362, 2023). "We detected the level of TBK1 activation (Phosphorylated TBK1, p-TBK1) in human HCC tissues and non-tumor liver tissues by western blotting, indicating that p-TBK1 was significantly up-regulated in HCCs compared with non-tumor liver tissues." (PMID 33679751, 2021). "Due to the lack of GRA4, a negative regulator that hijacks host TBK1, vaccination with ME49Δompdc/gra4 results in stronger IFN‐I responses and induces IFN‐I‐dependent CD11b+CD64+MAR‐1+ dendritic cells (DCs), which in turn activate potent T cell responses to prevent tumor growth." (PMID 39031880, 2024).
cancer (151 papers, 2009 to 2025). A tumor composed of atypical neoplastic, often pleomorphic cells that invade other tissues. "Dysregulation of TBK1 activity has been associated with the occurrence of multiple types of cancers, including NSCLC." (PMID 40412527, 2025). "TBK1 has a regulatory role in the growth and proliferation of cancer cells in inflammation-associated cancers." (PMID 40076567, 2025). "TBK1 has garnered significant attention as a prospective therapeutic target due to its role in signaling pathways associated with cancer." (PMID 38567349, 2024). "Dysregulation of TBK1 activity has been implicated in a variety of pathophysiologic conditions, including cancer." (PMID 39279883, 2024). "Genetic loss of TBK1 leads to embryonic lethality in mice, and its loss results in mitotic defects in cancer cell lines." (PMID 38059900, 2024). "There is evidence from animal models of cancer immunotherapy that the deletion of TBK1 in dendritic cells causes T cell activation, subsequently enhancing antitumor immunity." (PMID 39061024, 2024). "The pathway exerts its effects through downstream effector molecules, including TBK1, which has been associated with sustained inflammation and the progression of cancer." (PMID 38877472, 2024). "Studies have implicated TBK1 in facilitating cell survival, proliferation, and resistance to apoptosis, mechanisms that are inherently associated with cancer progression." (PMID 38567349, 2024). "In recent years, the association between TBK1 and tumors has been increasingly studied and involves a variety of cancer types." (PMID 36988258, 2023). "It is clear that additional, more detailed studies are required to elucidate the distinct roles of both TBK1 and IKKε across cancer types and mutational statuses, specifically within immune cell physiology." (PMID 35395857, 2022). "Detailed analyses of the roles of TBK1 with respect to both cancer type and mutational status will be required to best inform the investigation of TBK1 inhibitors in the treatment of cancer." (PMID 35395857, 2022). "Some studies have found that abnormal TBK1 can cause a variety of diseases and inhibiting the activity of TBK1 can slow or prevent the growth of cancer cells." (PMID 36142231, 2022). "Elevated TBK1 activity has implicated in the development of several cancers and elevated expression is associated with KRAS mutations and poor prognosis in PDAC." (PMID 34572737, 2021). "TBK1 activity is tightly controlled, but when dysregulated it is associated with inflammatory and autoimmune diseases and cancer." (PMID 34572737, 2021). "In the present study, we reported that variations in the levels of TBK1 expression were associated with prognosis in different types of cancer." (PMID 33679751, 2021). "Clearly, effects on mitosis should be considered as an underlying growth restrictive mechanism in cancers where TBK1 is inhibited." (PMID 30223576, 2018). "The interplay between TBK1 and autophagy is relatively clear in pathogenic responses but appears quite complex in cancer." (PMID 30223576, 2018). "To date, it appears that pain, inflammation, and cancer are associated with IKKε- or TBK1-specific NF-κB pathway activation while IRFs and the IFN pathways are involved in pathologies such as rheumatic diseases." (PMID 25997745, 2015). "Among them, TBK1 has been shown to be a drug target of interest in inflammation-associated cancers." (PMID 40076567, 2025). "Beyond direct antiviral applications, TBK1 is a known druggable target for a variety of conditions associated with its dysregulation, as well as a target of interest in the development of novel cancer immunotherapies (47, –, 49)." (PMID 41277846, 2025). "However, the precise molecular mechanisms underlying TBK1’s function in cancer biology, particularly how TBK1 regulates cancer immunology, need to be further investigated." (PMID 40412527, 2025).
cancer (continued). "Moreover, mechanisms underlying the anti-cancer effects of TBK1 inhibition should be explored to facilitate its clinical translation." (PMID 39744441, 2025). "Despite their structural similarity, there has been limited research to explore whether TBK1 and IKKε function together to promote cancer-associated phenotypes." (PMID 40738190, 2025). "Dysregulation of TBK1 has been linked to various human diseases, including cancer." (PMID 39279883, 2024). "In addition to its role in immunity, aberrant TBK1 activation has been implicated in the oncogenesis of several types of cancer, such as breast and non-small cell lung cancer (NSCLC)." (PMID 39061024, 2024). "As such, elevated TBK1 expression is associated with a poor prognosis in many cancer types." (PMID 35395857, 2022). "TBK1 is susceptible to hyperactivation in those cancer cells harboring KRAS-activating mutations." (PMID 35395857, 2022). "Furthermore, there are high mutations rates for TBK1 in cancer pair COAD and UCEC, and the expression of TMEM173 is positively associated with the infiltration of immune cells in cancer pair BRCA and THCA." (PMID 33505797, 2021). "TBK1 is shown to be essential in some human cancer cell lines with KRAS mutations." (PMID 34108518, 2021). "IKKε and TBK1 are also associated with the initiation and progression of several cancer types." (PMID 32630674, 2020). "We established that ERRα associates directly with TBK1; thus, ERRα might affect cancer progression as a substrate of the TBK1 kinase in addition to cooperating with TBK1 in the regulation of innate immune signaling." (PMID 28591144, 2017). "The upregulation of MYOC and TBK1 in both conditions may indicate involvement in inflammatory and oxidative stress pathways—mechanisms previously implicated in both neurodegeneration and cancer progression." (PMID 40808675, 2025). "Our results indicated that AOH1996 inhibited cancer stemness by increasing the protein level of p-TBK1." (PMID 41024256, 2025). "Innate immune sensors, such as RIG-I and cGAS have been described as mediators of immune cell-related death of cancer cells and promoters of TBK1 pathways." (PMID 41361170, 2025). "Specific genes commonly affected by ERK inhibition and TBK1–IKKε inhibition such as TRIM28 have been linked with stem cells and other cancer-associated mechanisms." (PMID 40738190, 2025). "It was reported that some KRAS mutant cancer cells displayed synthetic lethality with TBK1 knockdown." (PMID 40738190, 2025). "Mechanistically, AOH1996 induced cellular DNA damage, activated the cGAS–STING signaling pathway, suppressed cancer stemness by upregulating p-TBK1 expression, and promoted CD8+ T-cell-recruiting chemokines by stimulating IRF3-mediated transcription." (PMID 41024256, 2025). "As we have convincingly proved syntenin-1 as a substrate for TBK1 kinase, we continued to investigate the role of syntenin-1 phosphorylation by TBK1 in cancer biology." (PMID 40412527, 2025). "Using the STING agonist ADU-S100, researchers showed that STING activation decreases cancer cell viability, increases immune-enhancing cytokines IFNβ and IL-6, and activates the TBK1/NF-κB pathway, boosting immune activity." (PMID 39949780, 2025). "In conclusion, targeted inhibition of TBK1 can effectively treat various cancers, thus indicating TBK1 as a potential target for cancer therapy." (PMID 40076567, 2025). "Using quantitative PCR, we quantified IKKε (IKBKE) and TBK1 mRNA via normalization to a GUSB internal control in different KRAS mutant cancer cells." (PMID 40738190, 2025). "In HCC, TBK1 expression was significantly higher in cancer tissues than in normal tissues and correlated with the expression levels of hepatic inflammatory markers (liver fibrosis and platelet/albumin ratio)." (PMID 40076567, 2025). "We have provided evidence that CMA controls STING and TBK1 levels, thereby expanding the range of cancer-related proteins regulated by CMA." (PMID 40083918, 2025).
cancer (continued). "In cancer cells, TBK1 activity was shown to be regulated through the RalB–GTPase pathway, coupling innate immune signaling with cancer phenotypes." (PMID 40738190, 2025). "Previous studies have implicated PARP7 in IFN-I signaling using PARP7 inhibitors in cancer cells, although the mechanism remained unclear with TBK1 and NF-κB suggested as potential targets." (PMID 39969510, 2025). "Overall, the data suggest the importance of ERK regulation of IKKε, combined with roles for TBK1, in promoting oncogenic phenotypes associated with RAS-induced cancer cell signaling." (PMID 40738190, 2025). "This discovery holds particular significance given TBK1’s emerging role as a therapeutic target in oncology, especially for overcoming resistance to cancer immunotherapy." (PMID 40412527, 2025). "A previous study showed that increased expression of p-TBK1 inhibited the proliferation and maintenance of CSCs in cancer." (PMID 41024256, 2025). "We find that this regulation occurs in different cancer cells as well as organoid models, with limited effects on TBK1." (PMID 40738190, 2025). "This phosphorylation suggests that TBK1 modulates the activity of the anaphase-promoting complex/cyclosome, thereby influencing cell cycle dynamics and promoting cancer cell proliferation." (PMID 39744441, 2025). "By suppressing NF-κB signaling, TBK1 inhibition disrupts the pro-tumorigenic microenvironment and impedes cancer progression." (PMID 39744441, 2025). "Herein, we observed a significant decrease in AKT phosphorylation after TBK1 inhibition, indicating its involvement in mediating the anti-cancer effects." (PMID 39744441, 2025). "Mechanistically, AOH1996 induced cellular DNA damage, suppressed cancer stemness through the upregulation of p-TBK1, and promoted the secretion of CD8+ T-cell-recruiting chemokines by stimulating IRF3-mediated transcription." (PMID 41024256, 2025). "By disrupting critical signaling pathways, TBK1 inhibitors can effectively impair cancer cell survival and proliferation, thereby presenting a viable therapeutic strategy." (PMID 39744441, 2025). "In this review, we summarize the findings on mechanisms of TBK1 activation in cancer cells and recent discoveries that shed light on the direct upstream kinases promoting TBK1 activation." (PMID 39279883, 2024). "Generally, TBK1 acts as an oncogene and increased TBK1 activity, indicated by increased phosphorylation at the Ser172 residue, can be observed in multiple human cancers." (PMID 39279883, 2024). "Despite the growing interest of studying TBK1 in cancer biology and immunology, the precise mechanisms governing TBK1 activation in cancer cells remain incompletely understood." (PMID 39279883, 2024). "Multiple studies indicate that TBK1 has a role in cancer by facilitating cell survival, proliferation, and resistance to apoptosis, which is the programmed cell death process." (PMID 38567349, 2024). "The dysregulation of TBK1 has emerged as a significant contributing factor in various pathological conditions, including autoimmune disorders, neurological diseases, and cancer." (PMID 38567349, 2024). "Although the most direct mechanism of TBK1 activation in cancer cells remains not fully understood, several signaling pathways have been reported to induce TBK1 activation." (PMID 39279883, 2024). "In this minireview, we summarize various mechanisms contributing to TBK1 activation in different cancer cells, with a special focus on direct upstream kinases that promote TBK1 activity by phosphorylating the Ser172 residue." (PMID 39279883, 2024). "Here we reviewed the activation of TBK1 in cancer cells induced by multiple signaling components, such as RalB/Sec5/TBK1 complex, TBK1/TBKBP1/CARD10/PKC complex and TNFR1-SC complex." (PMID 39279883, 2024). "Previous experiments treating different cancer cell lines with TBK1 inhibitors or siRNAs showed an increase in the presence of supernumerary centrosomes and spindle poles." (PMID 38059900, 2024).
cancer (continued). "The convergence of TBK1’s roles in immune responses, inflammation, and cancer underscores its potential as a promising therapeutic target for cancer treatment." (PMID 38567349, 2024). "We anticipate further advancements in the development of TBK1 inhibitors as part of novel cancer treatment strategies." (PMID 39161768, 2024). "TBK1 has become a prospective therapeutic target and plays an increasingly important role in autoimmune diseases, metabolic diseases, and cancers." (PMID 36988258, 2023). "Despite the growing interest in studying the roles and regulation of TBK1 in cancer, the precise molecular mechanisms governing TBK1 signalling and its subsequent impact on cancer biology remain incompletely understood." (PMID 36928362, 2023). "Under hypoxic conditions, TBK1 was hyperactivated (increased pSer172) and stabilized, thereby promoting cancer cell growth." (PMID 36928362, 2023). "Our analysis of the Sequence Read Archive (SRA), Gene Expression Omnibus (GEO), and Asian Cancer Research Group (ACRG) databases showed that TRIM28 is positively associated with PD-L1, TBK1, and IRF1 at the transcriptional level." (PMID 37357254, 2023). "Our results revealed that in combination with radiation, ATM inhibitors offer a powerful new strategy for enhancement of DSB-mediated micronucleation and the TBK1-dependent inflammatory signaling in cancer cells." (PMID 36656721, 2023). "We discuss the molecular mechanisms by which TBK1 is regulated in cancer cells and, specifically, the role of TBK1 in the proliferation, survival, and immune system evasion of cancer cells." (PMID 35395857, 2022). "As such, TBK1 has been proposed to be a feasible target for pharmacological treatment of these types of cancer." (PMID 35395857, 2022). "In this review, we summarize advances in research into TBK1 signaling pathways and regulation, as well as recent studies on TBK1 in cancer pathogenesis." (PMID 35395857, 2022). "The CRC cells seemed to respond directly to TBK1-targeted drugs, several studies have reported the application of Amlexanox in cancer treatment and metabolism dysfunction, indicating the potential for adjuvant CRC therapy 40-43." (PMID 35637944, 2022). "In this review, we focus on the role of TBK1 in cancer development, progression, and metastasis in both preclinical animal models and clinical studies using patient samples." (PMID 35395857, 2022). "The IHC findings showed that the expression of GLUT1 increased from normal tissues to dysplasia and cancer tissues, which is consistent with the TBK1 level." (PMID 35637944, 2022). "The compound also inhibited the growth of cancer cell lines in non-small cell lung cancer by inhibiting TBK1, thereby leading to a reduction in downstream AKT signaling." (PMID 36172373, 2022). "Owing to the scope of its involvement and function in processes both within and outside the cancer cells, TBK1 has gained considerable interest as a possible drug target for cancer treatment." (PMID 35395857, 2022). "Recent studies suggested that TBK1 exhibited a significant role in mediating the process of survival probability and development in Kras-independent cancer cells." (PMID 36224658, 2022). "The results revealed that, in SCLC cells, aurora kinase B is a critical kinase for MYC amplification, and TANK-binding kinase 1 (TBK1) is crucial for cancer cell viability, G2/M arrest, and apoptosis." (PMID 35682614, 2022). "Tbk1-null cancer cells are more differentiated and less invasive than Tbk1-intact cancer cells in mice." (PMID 35395857, 2022). "For both cancer-predisposition genes NEK1 and TBK1, using gnomAD showed a much-improved significance level, compared with that using the study-specific control summary counts." (PMID 35545612, 2022). "U2OS was selected as the expression of TBK1 protein level is in the average range of cancer cells analyzed, is easily amenable to CRISPR-Cas9 and is a rather flat cell line ideal for immunofluorescence studies." (PMID 36415206, 2022).